STX18 (syntaxin 18)
Description:
Syntaxin that may be involved in targeting and fusion of Golgi-derived retrograde transport vesicles with the ER.
Synonyms: Ufe1
Tractability: Antibody: UniProt predicts a signal peptide or a membrane-spanning region; the Human Protein Atlas places it where antibodies can reach. PROTAC: ubiquitination databases record sites on it; its protein half-life has been measured.
Gene: Protein-coding gene on chromosome 4 (4,415,742 to 4,542,346, reverse strand). Ensembl gene ENSG00000168818.
Subcellular location: Endoplasmic reticulum membrane; Golgi apparatus membrane
Subcellular location (Human Protein Atlas): Endoplasmic reticulum; Plasma membrane
Pathways (Reactome):
Vesicle-mediated transport: COPI-dependent Golgi-to-ER retrograde traffic
Gene Ontology:
Molecular function: protein binding; protein domain specific binding; SNAP receptor activity
Biological process: endoplasmic reticulum membrane organization; positive regulation of ER to Golgi vesicle-mediated transport; positive regulation of organelle assembly; regulation of Golgi organization; retrograde vesicle-mediated transport, Golgi to endoplasmic reticulum; intracellular protein transport; membrane fusion
Cellular component: endoplasmic reticulum; plasma membrane; endoplasmic reticulum membrane; SNARE complex; Golgi membrane; membrane
Genetic constraint (gnomAD): Loss-of-function variants: 29 observed, 43.26 expected, observed/expected ratio (o/e) 0.67, 90% interval 0.5 to 0.91. The upper end of that interval is the gene's LOEUF score, 0.91, which puts it in group 3 of 6, group 1 being the genes least tolerant of losing a copy. Missense variants: 368 observed, 384.8 expected, observed/expected ratio (o/e) 0.96, 90% interval 0.88 to 1.04. Synonymous variants: 147 observed, 145.09 expected, observed/expected ratio (o/e) 1.01, 90% interval 0.88 to 1.16.
Homologues: Orthologues: macaque STX18 (99% identical), chimpanzee STX18 (98% identical), dog STX18 (96% identical), rat Stx18 (93% identical), mouse Stx18 (93% identical), guinea pig STX18 (92% identical), pig STX18 (81% identical), rabbit STX18 (78% identical), tropical clawed frog stx18 (74% identical), zebrafish stx18 (68% identical), Drosophila melanogaster Syx18 (38% identical), Caenorhabditis elegans syx-18 (29% identical).
Diseases named in the same sentence as STX18 in open-access papers:
STX18 is named in the same sentence as 17 diseases in open-access papers, as found by Europe PMC text mining. Sharing a sentence is not in itself a finding about the gene and the disease. The quoted sentences say what the papers report.
breast carcinoma (3 papers, 2019 to 2024). "Downregulation of STX18 was reported as significantly increasing growth of the MCF-7 human breast cancer cells." (PMID 32039004, 2019). "Downregulation of STX18 can significantly enhance the growth of MCF-7 breast cancer cells." (PMID 38903532, 2024).
endometrial cancer (2 papers, 2025). Primary or metastatic malignant neoplasm involving the endometrium (mucous membrane that lines the endometrial cavity). "Additionally, another study identified a a panel of fivegenes (ASRGL1, RHEX, SCGB2A1, SOX17, and STX18) as biomarkers for predicting lymph node metastasis in early-stage endometrial cancer patients." (PMID 39980551, 2025).
lung carcinoma (2 papers, 2022 to 2023). "Here, we demonstrate that knockdown of endogenous STX18 significantly reduced clonogenic survival of A549 and H460 lung cancer cells following X-radiation." (PMID 35668077, 2022). "In an unbiased functional genetic screen for radiosensitization targets in lung cancer, we identified syntaxin 18, a protein involved in retrograde vesicular transport between the Golgi apparatus and endoplasmic reticulum, as mediator of radioresistance." (PMID 35668077, 2022). "Downregulation of endogenous syntaxin 18 specifically reduced clonogenic survival of radioresistant and radiosensitive lung cancer cells following X-radiation." (PMID 35668077, 2022). "Interestingly, downregulation of syntaxin 18 in lung cancer cells also impaired expression of markers of epithelial-mesenchymal-transition, and reduced migration and invasion capacity." (PMID 35668077, 2022). "STX18 (syntaxin 18) mediates DNA damage response and promotes EMT in lung cancer, and LINC01224 (lncRNA 1224) is involved in colorectal cancer progression by sponging of miR-485-5p." (PMID 38203246, 2023).
neuroblastoma (2 papers, 2013 to 2017). Neuroblastoma (NB) is the most common solid, extracranial childhood tumor. "NBAS, initially identified as a gene that is co-amplified together with N-MYC in human neuroblastomas, was recently reported to encode a peripheral membrane protein that is a component of the Syntaxin 18 complex, which has a role in Golgi-to-endoplasmic reticulum retrograde transport." (PMID 23828042, 2013). "In addition to syntaxin 18, Rab18 interacts with ZW10 kinetochore protein (ZW10) and RAD50 interactor 1 (RINT1), which, together with neuroblastoma amplified gene (NAG), are members of the NRZ complex." (PMID 28815213, 2017).
atrial septal defect (1 paper, 2019). Interauricular communication is a congenital malformation characterized by a communication between the atrial chambers of the heart. "A locus in chromosome 4p16, adjacent to MSX1 and STX18, has been associated with atrial septal defects (ASD) in multiple European and Chinese cohorts." (PMID 31712678, 2019).
Cognitive impairment (1 paper, 2022). Abnormal cognition is characterized by deficits in thinking, reasoning, or remembering. "Leveraging an LPA-derived phenotype and genetics data, we identified two genome-wide significant loci in our genome-wide association analysis for LPAx (a data-derived cognitive impairment outcome): TEAD4 (rs11829294, p value = 2.40e-8) and STX18 (rs79453226, p value = 1.91e-8)." (PMID 35240980, 2022).
endometriosis (1 paper, 2022). The growth of functional endometrial tissue in anatomic sites outside the uterine body. "AEBP1 and HOXB6, together with IGF-1, CYP11A1, MMP-2, CC2D2A, IER3, STX18, maybe staging markers for endometriosis." (PMID 36532015, 2022).
liver failure (1 paper, 2021). A liver disease characterized by the liver losing or has lost all of its function. "Other diseases affecting STX18 complex function such as RINT1 deficiency, which is associated with recurrent liver failure and skeletal abnormalities and hence shows phenotypic overlap to NBAS deficiency, should be investigated for trafficking of cytolytic vesicles and impaired NK cell cytotoxicity." (PMID 34386911, 2021).
non-small cell lung carcinoma (1 paper, 2022). A group of at least three distinct histological types of lung cancer, including non-small cell squamous cell carcinoma, adenocarcinoma, and large cell carcinoma. "Nevertheless, our manuscript provides clues and evidence that STX18 is an important player in the radiation response in non-small-cell lung cancer, while genetic features modulating dependency on STX18 remain to be identified in future work." (PMID 35668077, 2022).
prostate tumors (1 paper, 2016). "Protein expression levels of all three analyzed autoantigens, SPAST, STX18 and SPOP were significantly deregulated either in primary prostate tumors and/or in late, castration-resistant tumor stages." (PMID 26863016, 2016).
infection (9 papers, 2016 to 2025). The state of being infected such as from the introduction of a foreign agent such as serum, vaccine, antigenic substance or organism. "Intriguingly, previous studies have implicated STX18 in PV entry and infection." (PMID 40431628, 2025). "Furthermore, we found that IGTP, TGTP1, and IFI47, which are LD-associated anti-infection proteins were all decreased in STX18 knockdown cells." (PMID 38245527, 2024). "Nonetheless, the reduction in HPV16 PsV infection observed when knocking down syntaxin 18 and the implication of syntaxin 18 in BKPyV trafficking raise an interesting question to explore." (PMID 35608352, 2022). "At 4 h post infection, the time in which the LCV is supposed to associate with the ER, the number of Sec61β-positive LCVs was significantly lower in cells silenced for Stx18 than in mock-treated cells." (PMID 33760868, 2021). "Knockdown of Rab18 and syntaxin 18 reduced TAg expression, indicating that both proteins are required for efficient infection." (PMID 28815213, 2017). "The results revealed the importance of Ras-related protein Rab18 and syntaxin 18 for BKPyV infection." (PMID 28815213, 2017). "Strikingly, infection of wild-type but not ΔdotA L. pneumophila promoted the association of 3x-FLAG-Rab6A with Stx18, p31, and BNIP1." (PMID 33760868, 2021). "The Rab18/NRZ/syntaxin 18 complex is required for BKPyV infection." (PMID 28815213, 2017). "Similarly, Stx18 silencing in Mtb-infected NHBE cells resulted in diminished MR1-dependent recognition of infection with Mtb." (PMID 27031111, 2016). "Furthermore, compared to non-infection, SARS-CoV-2 infection decreased the interaction between ATG14 and STX18." (PMID 38245527, 2024). "We have identified proteins, Stx18, VAMP4, and Rab6, which play a role in maintaining the structure of the TGN, and ultimately regulate the translocation of MR1 to the cell surface in the context of infection with Mtb." (PMID 27031111, 2016). "While knockdown of syntaxin 18, VAMP4 and Rab6 affected Mtb antigen presentation, only syntaxin 18 knockdown affected MR1 surface stabilization by 6-FP, suggesting distinct antigen presentation pathways between exogenously delivered antigens and an intracellular infection." (PMID 36430890, 2022). "Indeed, we found that Stx18, an ER membrane SNARE essential in endosome-to-ER delivery of BK PyV16, binds to EMC4 and EMC7, and also plays an important role in sorting SV40 to the ER to promote infection." (PMID 32111841, 2020). "Furthermore, infection and intracellular viability of Mtb were not affected by Stx18 silencing as demonstrated by quantitative culture of intracellular Mtb." (PMID 27031111, 2016).
tumor (7 papers, 2016 to 2025). "STX18 influences both cell cycle checkpoints and DNA damage repair mechanisms, thereby potentially reducing the susceptibility of tumor cells to radiation therapy." (PMID 40710178, 2025). "However, it is important to recognize that STX18 may also impact other biological processes associated with tumor progression, such as EMT and cell migration." (PMID 40710178, 2025). "For example, the intermodular crosstalk between Light-Yellow genes, TRPM4 and STX18, point to interactions between tumor proliferation and immune responses/vesicular trafficking." (PMID 39596419, 2024). "The connection between STX18 and the Green module genes suggests that vesicular transport may regulate the malignant phenotype by mediating communication between proliferating tumor cells and surrounding tissues." (PMID 39596419, 2024). "Analysis of protein expression within matched pairs of benign prostate tissue and corresponding tumor areas revealed an increased expression of SPAST and STX18 in most tumor samples whereas SPOP expression remained unchanged." (PMID 26863016, 2016).
cancer (3 papers, 2016 to 2024). A tumor composed of atypical neoplastic, often pleomorphic cells that invade other tissues. "SH3PXD2A and STX18 promote or inhibit the development of other cancers, consistent with our prognostic model." (PMID 38903532, 2024). "SPAST, SPOP and STX18 were found expressed in the epithelium of benign and cancer areas in both patient cohorts." (PMID 26863016, 2016). "While the role of STX18 in modulating sensitivity to irradiation is unknown, there are few functional studies suggesting a role for STX18 in cancer cells and in genomic stability." (PMID 35668077, 2022). "Immunohistochemistry and qPCR revealed that SPAST, STX18 and SPOP were expressed in the epithelium of benign and cancer areas of the high and the low inflammation cohorts." (PMID 26863016, 2016). "The expression pattern of three corresponding antigens were established in benign and cancer tissue by immunohistochemistry and qPCR: SPAST (Spastin), STX18 (Syntaxin 18) and SPOP (speckle-type POZ protein)." (PMID 26863016, 2016).
STX18 also shares sentences with these, for which no sentence is quoted: cholangiocarcinoma (1 paper); colorectal cancer (1); diabetes mellitus type 1 (1); prostate carcinoma (1).